YTHDC1 (YTH N6-methyladenosine RNA binding protein C1)
Diseases named in the same sentence as YTHDC1 in open-access papers (continued):
Sharing a sentence is not in itself a finding about the gene and the disease.
epilepsy (3 papers, 2022 to 2025). A brain disorder characterized by episodes of abnormally increased neuronal discharge resulting in transient episodes of sensory or motor neurological dysfunction, or psychic dysfunction. "The random forest (RF) model was applied to the screening, and seven m6A regulators (HNRNPC, WATP, RBM15, YTHDC1, YTHDC2, CBLL1, and RBMX) were selected as the candidate genes for predicting the risk of epilepsy." (PMID 36468034, 2022). "The qRT-PCR results indicated that WTAP and YTHDC1 have higher expression levels in patients with epilepsy, while HNRNPC was expressed to a lower level, which is consistent with our integrated analysis." (PMID 36468034, 2022). "Among these, seven genes-WTAP, HNRNPC, RBM15, CBLL1, YTHDC1, YTHDC2, and RBMX-exhibited distinct expression patterns between healthy individuals and those with epilepsy." (PMID 40530256, 2025). "For instance, whilst HNRNpc was expressed at a lower level in keeping with the findings of the integrated investigation, in patients with epilepsy WTAP and YTHDC1 displayed higher expression levels." (PMID 40530256, 2025). "Firstly, we analyzed the expression of 17 m6A-related genes extracted from a public dataset and found that seven of them (HNRNPC, WTAP, RBM15, YTHDC1, YTHDC2, CBLL1, and RBMX) were differentially expressed between patients with epilepsy and healthy individuals." (PMID 36468034, 2022).
fibrosis (3 papers, 2021 to 2025). the formation of excess fibrous connective tissue in an organ or tissue in a reparative or reactive process. "The Masson staining showed that cardiac fibrosis was increased in 8‐week‐old Ythdc1‐cKO mice." (PMID 34716659, 2021).
hypertrophic cardiomyopathy (3 papers, 2022 to 2024). A condition in which the myocardium is hypertrophied without an obvious cause. "Previous studies have reported that knockdown of YTHDC1 leads to inhibition of autophagy in keratinocytes, and loss of YTHDC1 has an inhibitory effect on mitophagy, which was identified as a biomarker of hypertrophic cardiomyopathy." (PMID 38877444, 2024).
lung adenocarcinoma (3 papers, 2020 to 2024). A carcinoma that arises from the lung and is characterized by the presence of malignant glandular epithelial cells. "Among these genes, KIAA1429, HNRNPC, YTHDC2, METTL3, WTAP, YTHDC1, and FTO were down expressed in lung adenocarcinoma, RBM15, ZC3H13, YTHDF1, YTHDF2, and ALKBH5 were up expressed." (PMID 32398949, 2020).
neuroblastoma (3 papers, 2021 to 2024). Neuroblastoma (NB) is the most common solid, extracranial childhood tumor. "Stratification analysis for association between YTHDC1 gene genotypes and neuroblastoma susceptibility." (PMID 34897032, 2021). "Association between YTHDC1 gene polymorphisms and neuroblastoma risk." (PMID 34897032, 2021).
renal carcinoma (3 papers, 2022 to 2025). A carcinoma arising from the epithelium of the renal parenchyma or the renal pelvis. "Next, we explored the underlying mechanism by which YTHDC1 inhibits the progression of renal cancer cells." (PMID 35974388, 2022). "Thus, our data suggest that YTHDC1 is abnormally downregulated in renal cancer tissues, downregulated YTHDC1 is associated with unfavorable prognosis, and YTHDC1 inhibits the progression of renal cancer in cells and in mice." (PMID 35974388, 2022). "The CCK-8 assay and Annexin V-FITC/propidium iodide staining assay demonstrated that knockdown of YTHDC1 decreased the sensitivity of renal cancer cells to sunitinib, but overexpression of YTHDC1 led to sunitinib resistance in renal cancer cells." (PMID 35974388, 2022). "We then demonstrated that treatment with ERK or MEK inhibitors (LY3214996 or GSK1120212, respectively) attenuated the effect of YTHDC1 on suppressing renal cancer cell proliferation." (PMID 35974388, 2022). "We showed that YTHDC1 inhibition promoted renal cancer cell proliferation, migration, and invasion in vitro." (PMID 35974388, 2022). "The following experiment was conducted to explore the regulatory mechanism of YTHDC1 in renal cancer cells." (PMID 35974388, 2022). "Together, our results demonstrate that YTHDC1 regulates the sensitivity of renal cancer cells to sunitinib through ANXA1." (PMID 35974388, 2022). "We found that CAY10683 treatment increased the protein and mRNA levels of YTHDC1 in renal cancer cells." (PMID 35974388, 2022). "Subsequently, we showed that YTHDC1 inhibits the progression of renal cancer cells via downregulation of the ANXA1/MAPK pathways." (PMID 35974388, 2022). "Subsequent in vitro and in vivo cell proliferation studies indicated that knockdown of ANXA1 blocked the effect of YTHDC1 on modulating the sensitivity of renal cancer cells to sunitinib." (PMID 35974388, 2022). "Together, these data indicate that YTHDC1 inactivates the MAPK signaling pathway to inhibit the proliferation of renal cancer cells." (PMID 35974388, 2022). "Western blot, quantitative real time PCR (RT‒qPCR), RNA immunoprecipitation PCR (RIP-qPCR), methylated RIP-qPCR (MeRIP-qPCR) and RNA sequencing (RNA-seq) analyses were applied to study the YY1/HDAC2/YTHDC1/ANXA1 axis in renal cancer cells." (PMID 35974388, 2022). "We found that overexpression of YTHDC1 decreased the phosphorylation of ERK in the shControl group but had no obvious effect on the phosphorylation of ERK in the shANXA1 group in renal cancer cells." (PMID 35974388, 2022). "Interestingly, we found that the HDAC2/YY1 complex suppressed YTHDC1 expression in renal cancer cells." (PMID 35974388, 2022). "Similarly, we demonstrated that the inhibitory effect on cell proliferation or invasion after overexpression of YTHDC1 was diminished in shANXA1 renal cancer cells." (PMID 35974388, 2022). "In addition, the nude mouse xenograft assay also demonstrated that knockdown of YTHDC1 increased the tumor growth of renal cancer cells." (PMID 35974388, 2022). "Moreover, IHC staining of the tissue microarray indicated that YTHDC1 was negatively correlated with ANXA1 in renal cancer." (PMID 35974388, 2022). "In contrast, overexpression of YTHDC1 decreased ANXA1 expression in renal cancer cells." (PMID 35974388, 2022). "However, the specific role and corresponding mechanism of YTHDC1 in renal cancer cells are still unclear." (PMID 35974388, 2022). "Because YTHDC1 has been reported to regulate the expression level of target genes by influencing their mRNA stability, we speculated whether ANXA1 was the downstream gene of YTHDC1 in renal cancer cells." (PMID 35974388, 2022). "Thus, investigating the regulatory mechanism of YTHDC1 would help identify novel chemicals to enhance the antitumor effect of TKIs in renal cancer cells." (PMID 35974388, 2022). "Next, we examined whether YY1 transcriptionally regulated the expression of YTHDC1 in renal cancer cells." (PMID 35974388, 2022).
renal carcinoma (continued). "In this study, ANXA1 was proven to be the downstream target gene of YTHDC1 in renal cancer cells." (PMID 35974388, 2022). "In contrast, overexpression of YTHDC1 decreased the phosphorylation of ERK in renal cancer cells." (PMID 35974388, 2022). "In contrast, overexpression of HDAC2 decreased the expression of YTHDC1 in renal cancer cells." (PMID 35974388, 2022). "Furthermore, HDAC2 inhibitors could promote the antitumor effect of sunitinib partially through YTHDC1 in renal cancer cells." (PMID 35974388, 2022). "Thus, we sought to determine whether YTHDC1 affects the activation of the MAPK signaling pathway in renal cancer cells." (PMID 35974388, 2022). "In renal cell carcinoma, YTHDC1 decreases mRNA stability of the downstream target gene ANXA1 in an m6A-dependent manner and decreases sunitinib sensitivity in renal cancer cells." (PMID 40435202, 2025). "Reactome enrichment analysis demonstrated that YTHDC1 was negatively correlated with EGFR and FGFR signaling pathways in renal cancer cells, which are reported to be the major driver pathways for the tumorigenesis of renal cancer." (PMID 35974388, 2022). "In contrast, we constructed ANXA1, YTHDC1 knockdown alone, or ANXA1 + YTHDC1 coknockdown renal cancer cells." (PMID 35974388, 2022). "First, we demonstrated that CAY10683 treatment decreased the IC50 values in the shControl group but not in renal cancer cells after YTHDC1 knockdown." (PMID 35974388, 2022). "We also showed that coknockdown of HDAC2 and YY1 did not further increase the expression of YTHDC1 in renal cancer cells." (PMID 35974388, 2022).
renal cell carcinoma (3 papers, 2022 to 2025). "We found that YTHDC1 expression was negatively correlated with the proliferation, invasion and metastasis of renal cell carcinoma cells." (PMID 35974388, 2022). "A Gene Set Enrichment Analysis (GSEA) of the TCGA-KIRC dataset demonstrated that low YTHDC1 expression was positively correlated with renal cell carcinoma and the mitogen-activated protein kinase (MAPK) signaling pathway." (PMID 35974388, 2022).
Sepsis (3 papers, 2020 to 2024). Sepsis is defined as life-threatening organ dysfunction caused by a dysregulated host response to infection. "In conclusion, Mir22hg was able to recruit the m6A reader YTHDC1 to stabilize Angptl4 mRNA expression, thereby promoting ferritinophagy to accelerate sepsis progression." (PMID 38842666, 2024). "In this predictive nomogram, the expression levels of FTO, HNRNPC, RBMX, YTHDC1, LRPPRC, and RBM15B were negatively associated with the risk score of patients with sepsis and were regarded as protective factors in sepsis." (PMID 36781867, 2023). "Mir22hg contributed to in ferritinophagy-mediated ferroptosis in sepsis via recruiting the m6A reader YTHDC1 and strengthening Angptl4 mRNA stability, highlighting that Mir22hg may be a potential target for sepsis treatment based on ferroptosis." (PMID 38842666, 2024). "The intersection of databases RM2Target, GSE179554-6 h, and GSE179554-12 h presented 7 genes (Mt1, Mt2, Alpl, Angptl4, Apod, Slc7a5, and Timp1) that may bind towards YTHDC1 in sepsis." (PMID 38842666, 2024).
thyroid cancer (3 papers, 2021 to 2024). "Morever, we found that YTHDC1 can promote the malignant behavior of thyroid cancer, such as proliferation and migration ability, through colony formation assays, CCK8 assays, and transwell assays." (PMID 38993572, 2024).
breast tumor (2 papers, 2022). "We analyzed patient survival and YTHDC1 gene expression data from The Cancer Genome Atlas (TCGA) cohorts and found that higher levels of YTHDC1 in breast tumors resulted in a significantly poorer prognosis." (PMID 35966596, 2022).
bronchopulmonary dysplasia (2 papers, 2024). Bronchopulmonary dysplasia is a chronic respiratory disease that results from complications related to lung injury during the treatment of infant acute respiratory distress syndrome in low-birth-weight premature infants or from abnormal lung development in older infants. "In alveolar epithelial cells from mice with bronchopulmonary dysplasia, inhibition of YTHDC1 led to a decrease in IL-33 mRNA and protein expression, which in turn inhibited alveolar epithelial cell apoptosis and alleviated lung injury induced by hyperoxia treatment for bronchopulmonary dysplasia." (PMID 39108751, 2024).
clear cell renal cell carcinoma (2 papers, 2023 to 2024). "In clear cell renal cell carcinoma, the YY1/HDAC2 complex reduces the expression of YTHDC1, which modulates the sensitivity of ccRCC to sunitinib by targeting the ANXA1-MAPK pathway." (PMID 37495623, 2023).
colitis (2 papers, 2023 to 2024). Inflammation of the colon. "The decreased expression of YTHDC1 in experimental colitis suggested its potential role in macrophage cells during intestinal inflammation." (PMID 38877444, 2024). "Here, we demonstrate that YTHDC1 is markedly decreased in DSS-induced colitis in vivo and in LPS/IFN-γ-stimulated RAW264.7 macrophages in vitro." (PMID 38877444, 2024). "Fecal microbiotas from IBD patients and Il10−/− mice developing colitis decrease gut macrophage YTHDC1 expression in wild‐type mice." (PMID 36922750, 2023). "Together, these results exhibited that sufficient YTHDC1 in macrophages is required to protect from colitis." (PMID 36922750, 2023). "Owing to the important protective roles of YTHDC1 in colitis development, we next sought to determine the levels of YTHDC1 in the macrophages derived from colonic tissues of IBD." (PMID 36922750, 2023). "Accordingly, YTHDC1 levels were also down‐regulated in the purified F4/80+Cd11b+macrophages from colitis animals compared to those of healthy controls." (PMID 36922750, 2023). "To explore the role of YTHDC1 in colitis, we established a colitis mouse model with DSS." (PMID 38877444, 2024). "Notably, macrophages with insufficient YTHDC1 accelerated colitis progression in both DSS‐induced and TNBS‐triggered animal models." (PMID 36922750, 2023). "Ythdc1 mRNA showed a robust decrease in the context of colitis." (PMID 36922750, 2023). "To resemble the insufficient, but not deleted, status of YTHDC1 in colitis, we crossed Ythdc1f/+ mice with LysM‐Cre mice to generate Ythdc1flox/+;Lysm‐Cre mice (hereafter referred to as mYthdc1+/−) with deficient YTHDC1 in macrophages." (PMID 36922750, 2023). "Together, these data demonstrate that fecal microbiotas from IBD patients or colitis mice could downregulate YTHDC1 levels in gut macrophages." (PMID 36922750, 2023). "In DSS-induced colitis and LPS/IFN-γ-treated RAW264.7 macrophages, we observed a significant downregulation of YTHDC1." (PMID 38877444, 2024). "In this study, we tested the functions of YTHDC1 in macrophages under IBD conditions by establishing both chemically induced and spontaneous colitis models using the Ythdc1f/f and mYthdc1−/− mice." (PMID 36922750, 2023). "To explore the molecular underpinning by which YTHDC1 in macrophages regulates colitis progression, we mined the published RNA‐sequencing database (GEO: GSE153512) concerning Mettl14f/f and Mettl14f/f;Lysm‐Cre BMDMs since YTHDC1 depends on RNA methylation to exert its functions." (PMID 36922750, 2023). "Our data illustrated that conditional knockout of Ythdc1 in neutrophils did not affect the development of colitis, confirming that the colitis phenotype of mYthdc1−/− mice was not attributed to neutrophils." (PMID 36922750, 2023). "We further confirmed that YTHDC1 mutant could not reverse body weight loss, clinical/histological scores, and IFN‐γ and IL‐17 increases in the TNBS‐induced colitis model." (PMID 36922750, 2023).
cutaneous melanoma (2 papers, 2021). A primary melanoma arising from atypical melanocytes in the skin. "In addition, WTAP, YTHDC1 and YTHDC2 are widely positively correlated with anti-tumor immune-related genes, while IGF2BP3 is widely negatively correlated with these genes, which may be involved in the immune escape of skin melanoma cells." (PMID 34737950, 2021).
Glucose intolerance (2 papers, 2025). Glucose intolerance (GI) can be defined as dysglycemia that comprises both prediabetes and diabetes. "Ythdc1-BKO mice exhibited significant glucose intolerance and insulin resistance compared to Ythdc1flox/flox mice." (PMID 40355558, 2025).
head and neck squamous cell carcinoma (2 papers, 2022 to 2024). A squamous cell carcinoma that arises from any of the following anatomic sites: lip and oral cavity, nasal cavity, paranasal sinuses, pharynx, larynx, and salivary glands. "According to previous studies, YTHDC1 promotes the stemness maintenance of head and neck squamous cell carcinoma stem cells and promotes disease progression." (PMID 39090090, 2024). "However, the role of YTHDC1 in head and neck squamous cell carcinoma (HNSCC) cancer stem cells remains largely unknown." (PMID 36411870, 2022).
Hyperglycemia (2 papers, 2023 to 2025). An increased concentration of glucose in the blood. "We also found that hyperglycemia induced by treatment with glucose but not hypertonic conditions did not change the mRNA level of YTHDC1 in T24 cells." (PMID 37258572, 2023). "Similarly, we showed that hyperglycemia induced by treatment with glucose (G) but not hypertonic conditions (mimicked by treatment with mannitol (M)) resulted in downregulation of YTHDC1 protein expression in T24 cells." (PMID 37258572, 2023).
inflammatory bowel disease (2 papers, 2023 to 2024). A spectrum of small and large bowel inflammatory diseases of unknown etiology. "It is revealed that YT521‐B homology‐domain‐containing protein 1 (YTHDC1) in gut macrophages is a novel factor responsible for the development of inflammatory bowel disease." (PMID 36922750, 2023). "However, the functional significance and regulatory mechanisms of YTHDC1 in inflammatory bowel disease (IBD) remain to be explored." (PMID 38877444, 2024). "Targeting YTHDC1 in gut macrophages might be an effective method for inflammatory bowel disease management." (PMID 36922750, 2023). "To date, the functions of YTHDC1 in immune cells as well as inflammatory bowel disease (IBD) are poorly understood." (PMID 36922750, 2023).
ischemia (2 papers, 2020 to 2022). A hypoperfusion of the BLOOD through an organ or tissue caused by a PATHOLOGIC CONSTRICTION or obstruction of its BLOOD VESSELS, or an absence of BLOOD CIRCULATION. "Besides, the induction of YTHDC1 was observed after ischemia, which was consistent with the previous report that the abundance of YTHDF1 and YTHDF2 was also altered after stroke." (PMID 33188203, 2020). "Another study found that knockdown of YTHDC1 aggravated ischemic brain injury, whereas overexpression of YTHDC1 increased phosphorylation of Akt by promoting the degradation of PTEN mRNA, thereby saving neurons after ischemia and protecting rats from cerebral ischemic damage." (PMID 36118889, 2022).
liver disease (2 papers, 2025). "Clinically, AP-2α expression negatively correlates with the expression of FASN, WTAP, YTHDC1 and the development of liver disease." (PMID 40180937, 2025). "The expression of AP-2α correlated negatively with the expression of WTAP, YTHDC1 and FASN in liver disease samples." (PMID 40180937, 2025).
male infertility (2 papers, 2024 to 2025). The inability of the male to effect fertilization of an ovum after a specified period of unprotected intercourse. "RNA‐seq and m6A‐seq analyses revealed that deletion of either Mettl6 or Ythdc1 disrupted the gene expression related to chromosome organisation and segregation, ultimately leading to male infertility." (PMID 39614650, 2025). "Conditional deletion of m6A "reader" proteins, Ythdf2, Ythdc1, and Ythdc2, in mouse germ cells has resulted in aberrant regulation of post-transcriptional m6A modification on mRNAs, leading to male infertility." (PMID 38363375, 2024). "The deletion of either Mettl16 or Ythdc1 with Stra8‐Cre disrupted the gene expression related to chromosome organisation and segregation, resulting in aberrant differentiation of spermatogonia and male infertility." (PMID 39614650, 2025).
myelodysplastic neoplasms (2 papers, 2024 to 2025). "In myelodysplastic neoplasms (MDS) with DDX41 mutations, the nuclear m6A reader YTHDC1 interacts with the METTL3–METTL14 complex to maintain genomic stability." (PMID 40973767, 2025).
osteoporosis (2 papers, 2023 to 2025). A condition of reduced bone mass, with decreased cortical thickness and a decrease in the number and size of the trabeculae of cancellous bone (but normal chemical composition), resulting in increased fracture incidence. "Our results demonstrated that the WTAP/YTHDC1/miR-181a and miR-181c/SFRP1 axis regulated the differentiation fate of BMSCs, suggesting that it might be a potential therapeutic target for osteoporosis." (PMID 36650131, 2023). "Our research revealed that WTAP could promote osteogenic differentiation and inhibit adipogenic differentiation of BMSCs through the YTHDC1/ miR-181a and miR-181c /SFRP1 axes, which could be of significance in developing therapeutic targets for osteoporosis." (PMID 36650131, 2023).